ARID1A (AT-rich interaction domain 1A)
Diseases named in the same sentence as ARID1A in open-access papers (continued):
Sharing a sentence is not in itself a finding about the gene and the disease.
gastric cancer (continued). "Knockdown of ARID1A in gastric cancer cell lines led to reduced E-cadherin (CDH1) expression, disruption of the cadherin/catenin complex, epithelial–mesenchymal transition, and enhanced invasive properties of the cells." (PMID 38275587, 2023). "This all‐encompassing review aims to dissect the potential of ARID1A as a valuable biomarker for immunotherapeutic approaches in gastric cancer, drawing from insights garnered from both preclinical experimentation and clinical observations." (PMID 38041544, 2023). "Dysregulated ARID1A expression can be detected in multiple malignancies, including gastric cancer, bladder cancer, and especially LUAD, ARID1A loss is associated with the significant enhancement of tumor metastasis and a poor prognosis." (PMID 36869329, 2023). "In contrast, the ratio of ARID1A loss in EBV‐negative, MLH1‐preserved gastric carcinoma cases was notably lower." (PMID 38041544, 2023). "In breast and gastric cancer, ARID1A-depleted cells showed an increased sensitivity to PI3K and AKT inhibitor compared to wild-type cells." (PMID 35070505, 2022). "Epstein–Barr virus-associated gastric cancer (EBVaGC) was one of four classifications of GC, with frequent mutations of PIK3CA, ARID1A, and BCOR, and PD-L1 and PD-L2 amplification; it accounts for up to 10% of its molecular subtypes." (PMID 36353623, 2022). "In a complementary panel of gastric cancer tumor cell lines, we found that two cell lines with ARID1A defects (YCC6 and SNU5) showed profound sensitivity to two different small-molecule ATRi, berzosertib and AZD6738." (PMID 36273494, 2022). "NF-κB directly bound to the promoter of miR-223-3p so that the expression of miR-223-3p was stimulated, and miR-223-3p played the oncogenic role in gastric cancer by directly targeting ARID1A." (PMID 35509814, 2022). "It was noted that several classic gastric cancer driver genes were more frequently mutated in the low-CDK6-AS1 expression group than in the high-expression group, such as ARID1A and PIK3CA." (PMID 35571043, 2022). "ARID1A cfDNA alterations were most frequent in endometrial cancer, 21.3% of patients; bladder cancer, 12.9%; gastric cancer, 11%; cholangiocarcinoma, 10.9%; and hepatocellular carcinoma, 10.6%." (PMID 36077815, 2022). "In particular, depletion of ARID1A (the YCC6 gastric cancer cell line used here is ARID1A mutant/defective), has been shown to repress RNA polymerase II (RNAPII) transcription." (PMID 36273494, 2022). "DNA damage-induced ATM activation promotes β-TRCP-mediated ubiquitination and destruction of ARID1A in gastric cancer cells, thereby exacerbating the development of gastric cancer." (PMID 36035159, 2022). "In gastric cancer cell lines, the silence of ARID1A increases the expression of vimentin and N-cadherin and promotes local lymph node metastasis and distant metastasis." (PMID 34671561, 2021). "In our previous study using ARID1A immunohistochemistry, the frequency of lost ARID1A was similarly high in early and advanced EBVaGC tumors but was increased in the advanced tumors of other gastric cancer subtypes." (PMID 34469459, 2021). "To test the possible contribution of lost ARID1A to the EBV infection of stomach epithelial cells, we infected ARID1A-knockdown and -knockout gastric cancer cells with EBV." (PMID 34469459, 2021).
gastric cancer (continued). "EBV-positive gastric cancers are reported to have recurrent mutations of PIK3CA, ARID1A, and BCOR and amplifications of JAK2, PD-L1, and PD-L224." (PMID 34873204, 2021). "Further, ARID1A deficiency was reported to activate phosphatidylinositol 3-kinase (PI3K)/protein kinase B (AKT) signaling and increased PD-L1 expression in gastric cancer." (PMID 34414106, 2021). "Loss of ARID1A is closely associated with MMR deficiency and MSI in gastric cancer, colorectal cancer, and uterine endometrioid carcinoma." (PMID 34671561, 2021). "This makes it possible to elucidate the role of the candidate ARID1A gene in the studied subjects as models for gastric cancer." (PMID 33801990, 2021). "Some mutations have been also observed in gastric cancer patients as well as Epstein-Barr virus infection including PIK3CA, ARID1A and BCOR mutations." (PMID 33024525, 2020). "In the TCGA cohort, gastric cancer (GC) harboring variants in RECQL4, ARID1A, MAGI1, or JAK3 were 4.5% (n = 20), 27.0% (n = 119), 7.5% (n = 33), or 3.8% (n = 17), respectively." (PMID 33328548, 2020). "In gastric cancer NCI-N87 cells, we have found that DNA damage treatment caused significant decrease of ARID1A protein levels which were drastically increased by the administration of MLN4924 or overexpression of a dominant negative Cullin1 mutant." (PMID 31210753, 2019). "In conclusion, the current study shows that ARID1A expression serves as a prognostic biomarker for gastric cancer." (PMID 31043675, 2019). "The in vitro experiment suggested that INF-α and INF-β were induced by ARID1A knockdown in gastric cancer cells." (PMID 31043675, 2019). "In the present study, we performed IHC staining for ARID1A in two independent cohorts of patients with surgically resected gastric cancer." (PMID 31043675, 2019). "ARID1A expression was evaluated using IHC staining in two independent cohorts of gastric cancer patients." (PMID 31043675, 2019). "Previously, we have reported that ARID1A protein was rapidly ubiquitinated and destructed in gastric cancer cells during DNA damage response." (PMID 31210753, 2019). "In this report, we verified the biological role of ARID1A in gastric cancer and found that ARID1A exerted the tumor suppressor role via regulating p21 and E-cadherin." (PMID 29317648, 2018). "In gastric cancer, ARID1A silencing enhanced the migration and invasion of gastric cancer cell lines via downregulation of E-cadherin expression." (PMID 29317648, 2018). "ARID1A expression was also reported to be a prognostic marker for several other cancers such as gastric cancer, clear cell renal cell carcinoma and cervical cancer." (PMID 29451900, 2018). "miR-223-3p promotes the proliferation and migration of gastric cancer cells by directly targeting ARID1A and decreasing its expression." (PMID 29317648, 2018).
gastric cancer (continued). "It has been reported that cyclin-dependent kinase inhibitor p21 is a downstream target of ARID1A in gynecologic cancers and ARID1A regulates gastric cancer cell migration and invasion via regulating E-cadherin expression." (PMID 29317648, 2018). "We transfected ARID1A-specific siRNA or ARID1A expression vector (pcDNA6.0-ARID1A) into the gastric cancer cells and detected the effect of ARID1A on cell proliferation and migration." (PMID 29317648, 2018). "Previous studies have demonstrated that decreased expression of ARID1A, which encodes another protein of the ARID family, enhances gastric cancer cell or HCC cell migration via transcriptional silencing of E-cadherin." (PMID 27351279, 2016). "To further investigate the clinicopathological and prognostic roles of ARID1A expression, we performed immunohistochemical analyses of the 224 paraffin-embedded gastric cancer tissue blocks." (PMID 22808142, 2012). "More interestingly, both studies demonstrated higher ARID1A alterations in gastric cancer samples with microsatellite instability (MSI) than those with microsatellite stability (MSS)." (PMID 22808142, 2012). "The cell growth assay revealed that cell growth rate in ARID1A-transfected gastric cancer cells were significantly lower than control vector-transfected gastric cancer cells." (PMID 22808142, 2012). "In the current study, we investigated the expression and prognosis value of ARID1A in primary gastric cancer." (PMID 22808142, 2012). "Restoring ARID1A expression in gastric cancer cells significantly inhibited cell proliferation and colony formation." (PMID 22808142, 2012). "In the present study, we analyzed the ARID1A expression level in gastric cancer using real-time quantitative RT-PCR, western blotting and immunohistochemistry." (PMID 22808142, 2012). "Meanwhile, the efficiency of colony formation was significantly (P = 0.0379) inhibited in ARID1A-transfected gastric cancer cells compared with control vector-transfected gastric cancer cells." (PMID 22808142, 2012). "Correlation between ARID1A expression and clinicopathological variables of 224 gastric cancer cases." (PMID 22808142, 2012). "Meanwhile, we identified the relationship between ARID1A expression and clinicopathological features and evaluated its prognostic value in post-resection survival of gastric cancer patients." (PMID 22808142, 2012). "In agreement with these molecular biological findings, immunohisto- chemistry with a anti-ARID1A antibody showed that ARID1A was completely silenced in 115 out of 224 patient gastric cancer samples, with positive expression in another 109 patients." (PMID 22808142, 2012). "Therefore, we can suggest that ARID1A, miR-129-5p and miR-3613-3p are aberrantly expressed in gastric cancer and involved in its tumorigenesis, and additional studies are needed to shed light on their functions and prognostic value." (PMID 39796161, 2025). "Furthermore, gastric tumors with MSI-high status and/or AT-rich interaction domain 1A (ARID1A) loss, molecular subtypes enriched in certain gastric cancer subsets, exhibit impaired HR and defective G2/M checkpoint control." (PMID 40869030, 2025). "In a subsequent study by the same authors, ARID1A loss was investigated by immunohistochemistry in early gastric cancer and non-neoplastic gastric mucosa." (PMID 38893181, 2024). "Besides, chromatin remodeling-related AT-rich interaction domain 1A (ARID1A) has been widely reported in stomach cancer formation." (PMID 38540967, 2024).
gastric cancer (continued). "While several studies have linked Arid1a loss to a worse prognosis in various cancers, such as ovarian, endometrial, colon, and gastric cancer, some studies suggest that the overexpression of Arid1a may also play a role in oncogenesis." (PMID 39123453, 2024). "Notably, ARID1A can effectively counteract the proliferation and invasion of gastric cancer cells that have an overexpression of miR‐223‐3‐p." (PMID 38041544, 2023). "There was a trend toward a higher TMB in HER2‐negative gastric cancer patients, particularly in patients with ARID1A mutation, though this was not statistically significant." (PMID 37325934, 2023). "Relative to HER2‐positive gastric cancer, HER2‐negative gastric tumors with ARID1A mutation may be sensitive to immune checkpoint inhibitors." (PMID 37325934, 2023). "The transfection of ARID1A gene in gastric cancer cell lines reduced cell proliferation while ARID1A silencing promoted proliferation and migration, thus confirming ARID1A tumor suppressive role in gastric cancer." (PMID 36890819, 2023). "Another study, encompassing 857 gastric carcinoma cases, including 67 EBV‐positive and 136 MLH1‐depleted cases (corresponding to the MSI‐high phenotype), identified frequent loss of ARID1A expression in EBV‐positive (34%) and MLH1‐deleted (29%) gastric carcinomas." (PMID 38041544, 2023). "AT-rich interactive domain 1A (ARID1A), also known as BAF250a, is a tumor suppressor that is typically mutated in Epstein-Barr virus-positive and microsatellite instability-high (MSI-H) gastric cancer, ovarian clear cell carcinoma, endometrial cancer, and non-small cell lung cancer." (PMID 36371186, 2022). "The reported ARID1A mutant prevalence in gastric cancer among different studies was 8–27%." (PMID 35421925, 2022). "Furthermore, miR‐223‐3p binds Arid1a to promote the proliferation and invasion of gastric cancer cells." (PMID 35588441, 2022). "According to the results of the pan-cancer analysis, we found that the abundances of CD4 + T cells and CD8 + T cells were significantly elevated in the mutated ARID1A, mutated ARID1B and mutated ARID2 groups, especially for colorectal cancer and gastric cancer." (PMID 35239432, 2022). "In addition, treatment of gastric cancer cell lines with the methyltransferase inhibitor 5-aza-2’-deoxycytidine increased ARID1A expression, which indicated the important role of DNA hypermethylation in ARID1A downregulation." (PMID 35611248, 2022). "To diagnose gastric cancer, we hypothesized that there are the associations of ID01778.3p-miR, ID00296.3p-miR, ID01702.3p-miR, and the ARID1A gene." (PMID 33801990, 2021). "The present results warrant further study of the value of ARID1A in gastric cancer." (PMID 31043675, 2019). "The prognostic value of ARID1A expression in gastric cancer was investigated next." (PMID 31043675, 2019). "Here, we found that negative ARID1A expression was associated with poor overall survival of patients with gastric cancer, especially in early-stage undifferentiated cases." (PMID 31043675, 2019). "ARID1A is highly mutated in EBV-positive gastric cancer, indicating that INF-α and INF-β may be induced by EBV infection as well as by ARID1A inactivation itself in ARID1A-mutated gastric cancer." (PMID 31043675, 2019).
gastric cancer (continued). "The present results indicate that ARID1A may serve as an early-stage prognostic biomarker for undifferentiated gastric cancer." (PMID 31043675, 2019). "EBVaGC comprises 5%–10% of gastric cancer cases and has several characteristics distinct from EBV-negative gastric cancers, such as massive lymphocytic infiltration, frequent genetic mutations in PIK3CA and ARID1A, and global hypermethylation of CpG islands." (PMID 30695048, 2019). "Since most ARID1A mutations in gastric cancer are truncating mutations that result in lack of ARID1A protein expression, immunohistochemical (IHC) staining can be used as a surrogate marker for ARID1A mutations." (PMID 31043675, 2019). "Therefore, we detected the protein levels of p21 and E-cadherin in the gastric cancer cells transfected with ARID1A siRNAs or pcDNA6.0-ARID1A." (PMID 29317648, 2018). "We found that the NF-κB/ miR-223-3p/ARID1A signaling cascade may be a 'bridge' for H. pylori-induced chronic inflammation to gastric cancer, thereby providing a new mechanism for the pathogenicity of H. pylori." (PMID 29317648, 2018). "In this study, we identified ARID1A as a novel direct target of miR-223-3p in gastric cancer." (PMID 29317648, 2018). "Therefore, we transfected the miR-223-3p mimics or inhibitor into gastric cancer cells and used qRT-PCR and western blot to determine the effect of miR-223-3p on the expression of ARID1A." (PMID 29317648, 2018). "The modulation mechanism of ARID1A for PI3K/AKT signaling in gastric cancer (GC) remains elusive." (PMID 27323812, 2016). "Considering both MSI and EBV infection, ARID1A loss was correlated with poor prognosis only in gastric cancers without MSI and EBV infection." (PMID 26384299, 2015). "Interestingly, ARID1A mutations are found in cancers with an epigenetic disposition, which include EBV and MSI groups in gastric cancer and the CIMP-high subtype in colorectal cancer (73–83% and 39%, respectively)." (PMID 25594067, 2014). "Our data suggest that ARID1A may play an important role in gastric cancer and may serve as a valuable prognostic marker and potential target for gene therapy in the treatment of gastric cancer." (PMID 22808142, 2012). "Furthermore, a multivariate Cox regression analysis confirmed the depth of tumor infiltration, local lymph node metastasis, distant metastasis and ARID1A expression as independent predictors of the overall survival of gastric cancer patients." (PMID 22808142, 2012). "Likewise, the ARID1A protein expression was remarkably decreased in gastric cancer cell lines, SGC7901, AGS, especially in MGC803, compared with normal gastric cell line GES1." (PMID 22808142, 2012). "Therefore, we evaluated the expression of ARID1A in gastric cancer by real-time PCR, western blotting and immunohistochemistry, in addition to its clinicopathological and prognostic significance in a large human sample." (PMID 22808142, 2012). "Twenty-four (75%) of the 32 gastric cancer samples with ARID1A mutations show either loss of or substantially reduced protein expression compared to those without ARID1A mutation." (PMID 22808142, 2012). "Furthermore, we evaluated the functional role of ARID1A in the tumorigenesis of primary gastric cancer by examining the in vitro proliferation and colony formation in gastric cell lines." (PMID 22808142, 2012). "However, SOX2 suppression may be permissive for a sub-set of gastric cancers with CDX2 induction to acquire mutations in epigenetic modifier genes, including ARID1A, KMT2D, KMT2C, KMT2A, and KMT2B." (PMID 40149431, 2025). "The link between the loss of ARID1A and MSI and TMB, together with PD-L1 expression, TILs and systemic inflammatory markers increases its clinical and prognostic relevance as a marker for screening and therapeutic response to targeted therapy and immune checkpoint inhibitors in gastric cancer." (PMID 39028418, 2024).